PF4 (platelet factor 4)
Diseases named in the same sentence as PF4 in open-access papers (continued):
Sharing a sentence is not in itself a finding about the gene and the disease.
Thrombocytopenia (continued). "This rare condition presents an extensive thrombosis with thrombocytopenia and the development of autoantibodies against platelet-factor 4 (PF4)." (PMID 34451494, 2021). "Laboratory investigations showed thrombocytopenia, raised D-dimer, and she was positive for PF4 antibodies." (PMID 34960150, 2021). "HIT occurs when specific antibodies bind to PF4/heparin complexes and result in cascading immune response, leading to thrombosis and thrombocytopenia." (PMID 34526009, 2021). "All three patients had thrombocytopaenia, high d-dimer levels, low fibrinogen levels and tested strongly positive for the presence of antibodies against PF4." (PMID 34613452, 2021). "Current developments in COVID and vaccine research have also highlighted the clinical significance of PF4 in PF4/polyanion complex formation and incidence of vaccine-mediated thrombocytopenia." (PMID 34526009, 2021). "They developed a grading system for identification of VITT based on features in the first reported cases (thrombocytopaenia, raised d-dimer, presence of PF4 antibodies and positive VITT assay)." (PMID 34613452, 2021). "These PF4/heparin antibodies then engage with platelets, leading to platelet activation and ultimately thrombocytopenia." (PMID 35126147, 2021). "Further management, including intravenous immune globulin and subsequent immunomodulation, hinges on the diagnosis of thrombotic complications in the presence of thrombocytopenia driven by a positive PF4 test." (PMID 34443589, 2021). "Implicated in VIPIT is the presence of autoantibodies targeting platelet factor 4 (PF4), which, along with thrombosis and/or thrombocytopenia, are part of the VIPIT diagnostic criteria." (PMID 34445670, 2021). "In these situations, anti-PF4 IgG antibodies elicit thrombus formation and thrombocytopenia via multiple mechanisms." (PMID 34029337, 2021). "Both patients developed thrombocytopenia with anti-PF4/polyanion antibodies, large cerebral infarct and venous pulmonary and portal vein thrombosis, within 10 days after ChAdOx1 nCoV-19 vaccination." (PMID 34341358, 2021). "The prevalence of thrombocytopenia and anti-PF4 antibodies was studied in 492 Norwegian health care workers 11 to 35 days after Vaxzevria vaccination; anti-PF4 antibodies with optical density values over a cutoff of ≥0.4 were detected in six (1.2%) vaccines." (PMID 34443589, 2021). "In the COVID-19 pandemic, thrombocytopenia occurring in vaccine-associated thrombosis has been called “COVID-19 vaccine-associated (immune) thrombosis and thrombocytopenia (VITT)”, often related to platelet factor 4 (PF4) antibodies." (PMID 34833382, 2021). "The bindings of HIT antibodies to platelets and the induction of thrombocytopenia are proportional to PF4 expression." (PMID 34639132, 2021). "Anti-PF4 antibodies would then recapitulate the sequence of events responsible for heparin-induced thrombocytopenia." (PMID 34029337, 2021). "Recent studies have assumed a mechanism that is assimilable to heparin-induced thrombocytopenia, with protagonist antibodies against the PF4-polyanion complex." (PMID 34912330, 2021). "This constellation of thrombotic disorders concurrently with thrombocytopenia and antibodies against PF4 resembles atypical or autoimmune heparin-induced thrombocytopenia, which happens even in the absence of previous exposure to heparin." (PMID 34802491, 2021). "These further enhance the platelet activation and in the presence of pre-existing anti-PF4 antibodies can lead to a heparin-induced thrombocytopenia-like disorder." (PMID 34290613, 2021). "Heparin-induced thrombocytopenia results from an autoantibody directed against platelet factor 4 in complex with heparin." (PMID 32953186, 2020). "In patients with HIT, antibodies against PF4/heparin complexes induce thrombocytopenia and thrombosis, even under situations when the platelet counts are low." (PMID 33050376, 2020).
Thrombocytopenia (continued). "Heparins interact with platelet factor 4 (PF4), which can induce an immune response causing thrombocytopenia." (PMID 31573759, 2020). "We classified 62 ND MM patients into thrombocytopenia group and platelet normal group in order to exclude the impact of platelet count upon PF4." (PMID 31043929, 2019). "PI-88 has also been reported to trigger thrombocytopenia in some patients and this was immunologically mediated as anti-heparin-PF4 complex antibodies were detected." (PMID 30845788, 2019). "The ADAPfl/fl PF4-Cretg mice resemble the phenotype of conventional ADAP knockout mice showing thrombocytopenia and augmented re-bleeding from tail wounds." (PMID 31632410, 2019). "This case series suggests that there was likely two mechanisms involving the thrombocytopenia; the IgG antibodies to heparin‐PF4 complex and the actual anaphylactic episode itself." (PMID 29701015, 2018). "Argatroban was started in 13 patients due to a clinical diagnosis of HIT, presenting with typical thrombocytopenia and positive laboratory testing for anti-pF4 antibodies." (PMID 28776204, 2017). "Consecutive antibody formation against PF4/heparin complexes is seen in 0.3–3% of patients on heparin treatment and mediates activation and clearance of platelets leading to thrombocytopenia and potentially thrombosis, the full manifestation of HIT." (PMID 28698883, 2017). "Argatroban was started in 13 patients (33%) due to suspected HIT, presenting with typical thrombocytopenia and positive laboratory testing for anti-PF4 antibodies." (PMID 28776204, 2017). "We diagnosed enoxaparin-induced thrombocytopaenia because of the clinical features, the patient’s heparin-naïve state and the laboratory finding of antibodies against PF4 and heparin complexes." (PMID 27080001, 2016). "Using hFcγRIIAtg mice it was identified that antibodies against heparin–platelet factor 4 complexes are responsible for hFcγRIIA-mediated platelet activation, thrombocytopenia, and thrombi formation in the lung vasculature." (PMID 24910634, 2014). "The positivity rate of the anti-PF4/heparin antibody is unrelated to the occurrence of thrombocytopenia, which is also consistent with previously reported results." (PMID 23646121, 2013). "The combination of a low to intermediate pretest probability with a negative PIFA test can rapidly exclude the presence of platelet activating anti-PF4/heparin antibodies and, therefore, HIT as the cause of the thrombocytopenia." (PMID 23876263, 2013). "Upon loss of Runx1 the program is abrogated leading to aberrant megakaryocytic maturation, sustained proliferation of FL-MKRunx1−/− and thrombocytopenia in Runx1F/F/Pf4-Cre mice." (PMID 23717578, 2013). "Until recently, PF-4 has been studied in the past mainly in the setting of heparin-induced thrombocytopenia." (PMID 23800319, 2013). "It is when certain HIT antibodies bind their PF4 antigen, forming immune complexes, that subsequent Fc-gamma receptor-mediated platelet activation ensues and can lead to thrombocytopenia and/or thrombosis." (PMID 23561460, 2013). "In critically ill patients with thrombocytopenia and heparin exposure, the presence of anti-PF4/heparin antibody ranges between 10% and 30%, but the actual incidence of HIT appears to be 1% or less." (PMID 23876263, 2013). "Heparin-induced thrombocytopenia is an immune response mediated by anti-PF4/heparin antibody, which is clinically characterized by thrombocytopenia and thromboembolic events." (PMID 23646121, 2013). "The diagnosis of HIT is based on clinical criteria, including thrombocytopenia, which is confirmed by in vitro demonstration of anti-PF4/heparin antibodies using functional and immunological methods." (PMID 21261941, 2011). "PF4 has been most studied in the context of heparin induced thrombocytopenia during which PF4-heparin complexes are immunogenic and lead to antibody mediated platelet destruction." (PMID 20454664, 2010).
Thrombocytopenia (continued). "• Heparin-induced thrombocytopenia diagnosis and positive anti-PF4/heparin antibody were frequently observed in the case of repeated hemofiltration-filter clotting during continuous veno-venous hemofiltration (CVVH) under heparin." (PMID 18578859, 2008). "The results from both preclinical studies in rats and a human clinical trial with BMS-986158 treatment revealed that Nuclear Factor Erythroid 2 (NFE2) and Platelet Factor 4 (PF4, CXCL4) genes are desirable biomarkers for predicting the risk of thrombocytopenia following BET inhibition." (PMID 40937321, 2025). "This promotes the thrombosis and thrombocytopenia characteristic of anti‐PF4 disorders." (PMID 40589323, 2025). "Furthermore, our findings demonstrate the translatability of NFE2 and PF4 from preclinical to clinical settings, making them valuable tools for predicting and monitoring thrombocytopenia, and potentially anemia." (PMID 40937321, 2025). "The antibody–antigen complex then causes platelet activation by binding to platelet FcγRIIA receptors, promoting a pro‐thrombotic state, that is, further release of PF4, platelet aggregation, release of procoagulant microparticles, as well as calpain‐dependent thrombocytopenia." (PMID 40589323, 2025). "It is associated with the presence of anti-platelet factor 4 (PF4) antibodies in the absence of prior heparin exposure, mimicking the mechanism of heparin-induced thrombocytopenia." (PMID 41427155, 2025). "The timely identification of an underlying anti-PF4 disorder in patients with thrombocytopenia with or without thrombosis is crucial for successful therapy." (PMID 40236285, 2025). "Further investigation into the use of NFE2 and PF4 as early biomarkers could improve our ability both to predict and manage drug induced thrombocytopenia." (PMID 40937321, 2025). "This promotes the thrombocytopenia and thrombosis characteristic of anti‐PF4 disorders." (PMID 40589323, 2025). "The mean platelet count in this study cohort was 97.2 × 103/uL, indicating that the DIC with thrombocytopenia may contribute to the decreased PF4 levels observed in these patients." (PMID 40864331, 2025). "GATA1 affects NFE2 and PF4, influencing thrombopoiesis and leading to thrombocytopenia." (PMID 40937321, 2025). "The clinical timing of platelet fall (5-10 days post-heparin initiation), magnitude of thrombocytopenia (greater than 50% decline), and new thrombosis, in conjunction with a strongly positive PF4 ELISA and confirmatory SRA, supported the diagnosis of type 2 HIT as the most plausible etiology." (PMID 41450710, 2025). "This condition may be due to the interaction between Ad hexon and platelet factor-4 (PF4), forming immune complexes that activate platelets and lead to thrombocytopenia." (PMID 39852874, 2025). "More commonly, however, non-pathogenic anti-PF4 antibodies or simply elevated PF4 levels can subtly shift perioperative haemostasis without overt thrombocytopenia." (PMID 41303146, 2025). "Diagnostic criteria for this condition include unexplained thrombocytopenia and/or thrombosis without recent heparin exposure and demonstration of anti-PF4 antibodies of the IgG subclass that cause strong in vitro platelet activation in the absence of heparin." (PMID 41552073, 2025). "However, removal of platelets in HIT is mainly by macrophages and neutrophils as discussed in the section on pathogenesis below (see Pathogenesis of thrombosis and thrombocytopenia in anti‐PF4 disorders)." (PMID 40589323, 2025). "•If thrombosis and thrombocytopenia occur together, anti-PF4 disorders should be considered." (PMID 40236285, 2025). "Type 2 HIT is an antibody-mediated, prothrombotic drug reaction first described in 1973, characterized by thrombocytopenia occurring about one week after heparin initiation, frequent thrombotic events, and the presence of heparin-dependent, platelet-activating anti-PF4 antibodies." (PMID 40276517, 2025).
Thrombocytopenia (continued). "Unlike other anti-platelet factor 4 (PF4) antibody-mediated disorders, such as heparin-induced thrombocytopenia (HIT), VITT arises with the development of platelet-activating anti-PF4 antibodies 4–42 days post-vaccination, typically featuring thrombocytopenia and thrombosis at unusual sites." (PMID 38398325, 2024). "All definitions require evidence of thrombocytopenia and anti-PF4 antibodies." (PMID 38787838, 2024). "The elevation of platelet and coagulation-related factors such as PF4 (CXCL4), also regulated by IL-6, may be related to the increased incidence of thrombocytopenia among PWID." (PMID 38920641, 2024). "To investigate this potential influence of metal cations in heparin-treated patients, we tested for association and correlation of plasma cation concentrations with markers of anti-PF4/heparin antibody production, including antibody titers and extent of thrombocytopenia." (PMID 38798628, 2024). "Isolated thrombocytopenia (without thrombosis) has been described with mRNA-based COVID-19 vaccines and a pathogenic platelet factor-4 (PF4)-dependent syndrome leading to thrombotic thrombocytopenia after vaccination with ChAdOx1 nCov-19." (PMID 36670100, 2023). "The majority had thrombocytopenia, high D-dimer, and anti-PF4 antibodies." (PMID 37182082, 2023). "An IgG-κ type monoclonal paraprotein, which binds to PF4 and activates platelets via their FcγIIa receptor, has been identified in this patient who presented with recurrent deep vein thrombosis, pulmonary embolism, stroke and thrombocytopenia." (PMID 37834770, 2023). "All patients had severe or moderate thrombocytopenia and the presence of anti-PF4 antibodies." (PMID 37893186, 2023). "The hallmark features are thrombocytopenia, thrombosis within 5–30 days of adenoviral SARS-CoV-2 vaccination, with strikingly elevated levels of D-dimer, hypofibrinogenemia, and positive antibodies against platelet factor 4 (PF4)." (PMID 37351283, 2023). "VITT is diagnosed 5–30 days post-vaccination and clinically characterized by thrombocytopenia, strongly elevated D-dimer levels, platelet-activating anti-platelet factor 4 (PF4) antibodies and thrombosis, especially at atypical sites such as the cerebral venous sinus and/or splanchnic veins." (PMID 37834770, 2023). "Furthermore, ontogeny data for proteins implicated in ASO-induced thrombocytopenia mechanisms, such as GPVI and PF4, are pivotal to extending the work to juvenile minipigs as a nonclinical safety model for pediatric drug development." (PMID 37111598, 2023). "Moreover, the differential abundance of GPVI and PF4 in minipigs provides insight into the influence of ontogeny in potential ASO-induced thrombocytopenia in pediatric patients." (PMID 37111598, 2023). "Regenerative thrombocytopenia was either achieved by diphtheria toxin (DT)-induced apoptosis of megakaryocytes in the bone marrow of transgenic megakaryocyte specific iDTR mice (PF4 iDTR) or by anti-GPIbα antibody (R300)-mediated depletion of platelets in the circulation." (PMID 37830633, 2023). "These events were termed vaccine‐induced immune thrombotic thrombocytopenia (VITT) with five criteria, including the history of recent vaccination, thrombotic complications mostly at unusual sites, thrombocytopenia, increased D‐dimer levels, and positivity of anti‐PF4 antibody." (PMID 37323251, 2023). "An increasing number of patients are currently identified with platelet-activating anti-PF4 antibodies causing thrombocytopenia and thrombosis, but without previous heparin exposure or vaccination." (PMID 37834770, 2023). "According to this study, patients who develop thrombotic symptoms after receiving COVID-19 vaccine should be examined for thrombocytopenia, elevated D-dimer, and/or reduced fibrinogen, as well as anti-PF4 ELISA testing in the brain, central venous sinus, and abdomen." (PMID 35923492, 2022).
Thrombocytopenia (continued). "In addition to laboratory testing for the presence of thrombocytopenia, the presence of antibodies against PF4/H is initially investigated by immunological testing, for which a variety of assays have now become available." (PMID 35225866, 2022). "Most patients still have thrombocytopenia and PF4 antibodies after discharge from the hospital." (PMID 35449682, 2022). "These B-cells then produce anti-PF4 antibodies, which form immune-complexes after binding to PF4 and trigger platelet activation with the FcyRIIa part of the anti-PF4 antibodies, leading to thrombocytopenia and contributing to thrombosis." (PMID 36351906, 2022). "First, thrombosis is caused by anti-PF4 antibodies that activate platelets only at specific sites and do not cause thrombocytopenia [thrombosis with anti-PF4 antibodies without thrombocytopenia syndrome (T4-noTS)]." (PMID 36247442, 2022). "VITT/VIPITT is defined as presence of venous or arterial thrombosis, thrombocytopenia, and autoantibodies (anti-PF4–polyanion or anti-PF4–heparin antibodies) within 5–30 days of vaccination with either AstraZeneca or Janssen/Johnson & Johnson COVID-19 vaccines." (PMID 35865539, 2022). "To assess whether anti-PF4 antibodies are responsible for the clinical features of thrombocytopenia and thrombosis in VITT patients, we used a FcγRIIa+/hPF4+ double transgenic mouse model." (PMID 36064843, 2022). "The occurrence of both severe thrombocytopenia and extensive venous thrombosis in the presence of detectable antibodies against anti-PF4, as well as marked elevation of D-dimer occurring within 30 days of vaccination, fulfills all five diagnostic criteria for VITT." (PMID 36560433, 2022). "IgG antibodies to native PF4 may contribute to more severe and persistent thrombocytopenia, and their detection could be useful in clinical practice." (PMID 35971886, 2022). "The diagnostic algorithm included the execution of a screening test for HIT in order to detect antibodies against PF4 in patients developing confirmed thrombosis and/or thrombocytopenia between days four and sixteen after receiving a ChAdOx1 nCoV-19 vaccination." (PMID 35740269, 2022). "It was recently demonstrated that in several cases of individuals with thrombotic events and thrombocytopenia after ChAdOx1 nCoV-91 vaccination, who elicited antibody responses against platelet factor 4 (PF4)-heparin, also generated antibodies against PF4 independent of heparin." (PMID 34356644, 2021). "PF4 plays an important role in development of sepsis induced thrombocytopenia." (PMID 34573990, 2021). "Antibodies against platelet factor 4 (PF4) can be detected on platelets of subjects that develop thrombocytopenia after vaccines in about 79% of cases; thus, it may be considered as immune thrombocytopenia." (PMID 34684034, 2021). "The progression of this possible vaccine-induced anti-PF4 autoimmune response could be related to mechanisms similar to those for prothrombotic thrombocytopenia induced by the SARS-CoV-2 virus itself." (PMID 34443589, 2021). "Alternatively, heparin might activate anti-PF4 antibodies after ChAdOx1 nCoV-19 vaccination, resulting in heparin-induced thrombocytopenia." (PMID 34356644, 2021). "In addition, a heparin‐induced thrombocytopenia‐like mechanism through the induction of anti‐platelet factor 4 IgG antibodies has also been proposed, based on the binding of nucleic acids to platelet factor 4, although contradictory results have been reported." (PMID 33821570, 2021). "As the clinical presentation is often reminiscent of heparin-induced thrombocytopenia, the hypothesis of a vaccine-induced autoimmune response to PF4 was put forward." (PMID 34029337, 2021). "Next to platelet activation, other lab findings such as thrombocytopenia, a reduction in fibrinogen, elevated D-Dimers, and circulating antibodies against platelet factor 4 (PF-4) may aid in diagnosing VITT." (PMID 34202817, 2021).